CLEC4E (C-type lectin domain family 4 member E)
Description:
Calcium-dependent lectin that acts as a pattern recognition receptor (PRR) of the innate immune system: recognizes damage-associated molecular patterns (DAMPs) of abnormal self and pathogen-associated molecular patterns (PAMPs) of bacteria and fungi. The PAMPs notably include mycobacterial trehalose 6,6'-dimycolate (TDM), a cell wall glycolipid with potent adjuvant immunomodulatory functions. Interacts with signaling adapter Fc receptor gamma chain/FCER1G to form a functional complex in myeloid cells (By similarity). Binding of mycobacterial trehalose 6,6'-dimycolate (TDM) to this receptor complex leads to phosphorylation of the immunoreceptor tyrosine-based activation motif (ITAM) of FCER1G, triggering activation of SYK, CARD9 and NF-kappa-B, consequently driving maturation of antigen-presenting cells and shaping antigen-specific priming of T-cells toward effector T-helper 1 and T-helper 17 cell subtypes (By similarity). Also recognizes alpha-mannose residues on pathogenic fungi of the genus Malassezia and mediates macrophage activation (By similarity). Through recognition of DAMPs released upon nonhomeostatic cell death, enables immune sensing of damaged self and promotes inflammatory cell infiltration into the damaged tissue (By similarity).
Synonyms: MINCLE; CLECSF9
Tractability: Antibody: UniProt places it where antibodies can reach, with high confidence; its Gene Ontology location is reachable by antibodies, with high confidence; UniProt predicts a signal peptide or a membrane-spanning region.
Target class: Membrane receptor
Gene: Protein-coding gene on chromosome 12 (8,533,305 to 8,540,905, reverse strand). Ensembl gene ENSG00000166523.
Subcellular location: Cell membrane; Cell projection, phagocytic cup
Pathways (Reactome):
Immune System: Dectin-2 family
Gene Ontology:
Molecular function: calcium ion binding; pattern recognition receptor activity; protein binding; carbohydrate binding; glycolipid binding; signaling receptor activity
Biological process: pattern recognition receptor signaling pathway; antifungal innate immune response; innate immune response; immune response; immune response-regulating signaling pathway; immune system process; positive regulation of cytokine production
Cellular component: membrane; plasma membrane; external side of plasma membrane; phagocytic vesicle membrane; phagocytic cup
Genetic constraint (gnomAD): Loss-of-function variants: 11 observed, 12.02 expected, observed/expected ratio (o/e) 0.91, 90% interval 0.57 to 1.51. The upper end of that interval is the gene's LOEUF score, 1.51, which puts it in group 6 of 6, group 1 being the genes least tolerant of losing a copy. Missense variants: 125 observed, 144.64 expected, observed/expected ratio (o/e) 0.86, 90% interval 0.75 to 1. Synonymous variants: 56 observed, 49.59 expected, observed/expected ratio (o/e) 1.13, 90% interval 0.91 to 1.41.
Homologues: Orthologues: chimpanzee CLEC4E (99% identical), macaque CLEC4E (89% identical), rabbit CLEC4E (70% identical), rat Clec4e (66% identical), mouse Clec4e (65% identical), guinea pig CLEC4E (64% identical), Caenorhabditis elegans clec-91 (20% identical), Caenorhabditis elegans clec-266 (20% identical), Caenorhabditis elegans clec-88 (19% identical), Caenorhabditis elegans clec-87 (18% identical), Drosophila melanogaster lectin-33A (14% identical), Drosophila melanogaster CG34033 (12% identical), and 3 more. Paralogues in human: CLEC6A (37% identical), CLEC4C (36% identical), CLEC4A (35% identical), CLEC4D (35% identical), CD209 (31% identical), CLEC10A (30% identical), CLEC4M (30% identical), ASGR2 (29% identical), CLEC17A (29% identical), CLEC4G (27% identical), ASGR1 (27% identical), CD207 (24% identical), and 2 more.